DDR1 (discoidin domain receptor tyrosine kinase 1)
Diseases named in the same sentence as DDR1 in open-access papers (continued):
Sharing a sentence is not in itself a finding about the gene and the disease.
cancer (continued). "Our results illustrated that DDR1 expression was highly correlated with MMR gene expression, MSI, and TMB in most cancers." (PMID 37031216, 2023). "Our data revealed that DDR1 expression was negatively correlated with M0 macrophages and activated CD4 memory T cells in most cancers." (PMID 37031216, 2023). "Intriguingly, the expressions of TIGIT and CD28 were positively correlated with those of DDR1 in LAML and LIHC but negatively correlated with those of DDR1 expression in the other 17 cancers." (PMID 37031216, 2023). "Our results therefore reveal a new mode of DDR1 regulation in PDAC and probably in other desmoplastic cancers." (PMID 36198801, 2022). "Some collagens also bind and activate receptor tyrosine kinases discoidin domain receptors (DDR1 and DDR2) that are thought to mediate metastases and cancer aggressiveness." (PMID 35008401, 2022). "Inhibitors targeting discoidin domain receptor 1 (DDR1), BAY-826 and DDR-IN-1 are promising hits as DDR1 inhibition has potential in cancer therapy." (PMID 35559262, 2022). "Together, these results provide evidence that DDR1 stimulates CXCL5 production through a PKCθ/SYK/NF-κB signaling cascade and that CXCL5 from cancer cells induces neutrophils to form NETs and thereby enhances metastasis." (PMID 34237033, 2021). "Discoidin domain receptors (DDR1 and DDR2) are the collagen receptors of the family tyrosine kinases, which play significant role in the diseases like inflammation, fibrosis and cancer." (PMID 34145346, 2021). "Thus, we investigated whether NETs contributed to DDR1-induced cancer cell invasion." (PMID 34237033, 2021). "Patients with DDR2 cancer had a higher DDR score and benefited less from traditional treatment than patients with DDR1 cancer, but the DDR2 type was significantly related to a longer survival time with immunotherapy." (PMID 34335575, 2021). "Specifically, we identified CXCL5 as a key chemokine in collagen I-induced NET formation and show that the pharmacologic blockade of DDR1 effectively prevents collagen induction of CXCL5, subsequent NET formation, and cancer cell invasion." (PMID 34237033, 2021). "The exposure of parental cancer cells to collagen I for 3 hours increased mRNA and protein levels of CXCL5 in MDA-PATC 148 and BxPC-3 cells, which was diminished in knockdown DDR1 cells." (PMID 34237033, 2021). "These carefully designed studies demonstrate that CXCL5 is a soluble factor released into the media from DDR1-positive cancer cells in the presence of collagen; when exposed to CXCL5, neutrophils generate NETs that promote cancer cell invasion." (PMID 34237033, 2021). "Aside from the main role of DDR1 and DDR2 in human cancer, they are also involved in other disorders such as inflammation, tissue fibrosis and atherosclerosis, and neurodegenerative diseases." (PMID 34207360, 2021). "In our studies, we observed a decrease in NE activity through DDR1 knockdown, NE inhibitors, and heat treatment; all of these conditions prevented NET-mediated cancer cell invasion, highlighting the contribution of NE during PDAC cell invasion." (PMID 34237033, 2021). "There are not many studies that focused on the analysis of the impact of DDR1 and DDR2 within the same cancer, although, very often, both receptors are expressed." (PMID 33917302, 2021). "All the new compounds were evaluated for their biological properties toward extracellular matrix in rat renal proximal tubular cells, human cancer cells (K562, A549, and Huh7), EV71, ROCK2, JAK3, DDR1, and coagulation." (PMID 32876846, 2021). "Since their discovery more than 20 years ago, the DDR1 and DDR2 collagen receptors are considered critical regulators of cancer invasion." (PMID 32117772, 2020). "Dual immunohistochemical staining further confirmed the spatial locations of DDR1 and PDPN in OSCC tissues indicative of collective cancer cell invasion." (PMID 32244515, 2020).
cancer (continued). "Here, we review recent findings on the metastatic role of the collagen receptors Discoidin Domain Receptors 1 and 2 (DDR1 and DDR2) in CRC and discuss the therapeutic value of targeting these receptor tyrosine kinases in this cancer." (PMID 32117772, 2020). "As a whole, this set of experiments demonstrates that DDR1 is expressed and is functional in A375, HT29 and SK-HEP human cancer cells." (PMID 32090682, 2020). "In summary, the present study provided two potential oncogenic roles of DDR1 in OSCC pathogenesis: prosurvival cell growth and collective cancer cell invasion." (PMID 32244515, 2020). "Using this strategy in NSCLC in the present study, we have found that TMPRSS4 is co-overexpressed with Discoidin Domain Receptor tyrosine kinase 1 (DDR1), a membrane protein that promotes cancer cell growth and dissemination." (PMID 31659178, 2019). "It is worth noticing that the degree of promoter methylation found for DDR1 is highly correlated with that of TMPRSS4 in NSCLC patients and cancer cell lines." (PMID 31659178, 2019). "In MCF-7 and highly metastatic MDA-MB-231 human BC cells, stimulation with IGF-1 induces the overexpression of discoidin domain receptor 1 (DDR1), a collagen receptor tyrosine-kinase involved in EMT-dependent cancer progression." (PMID 30111747, 2018). "Activation of the PI3K/Akt pathway plays an important role in cancer tumorigenesis and progression and it has been reported PI3K and Akt are a downstream target of DDR1 activation." (PMID 29559654, 2018). "Thus, DDR1 may work as a possible novel candidate in targeting the IGF-2/IR-A loop in cancer." (PMID 28591735, 2017). "In this context, it has recently been reported that DDR1 enhances the formation of invadosomes and MMP activity in cancer cells via the small GTPase Cdc42." (PMID 27391444, 2016). "Cancer cell proliferation at metastatic sites is likewise induced by the interaction between collagen and noncanonical discoidin domain receptor 1 (DDR1)." (PMID 41383620, 2025). "Similarly, the involvement of another ColI receptor, Ddr1, is unlikely, given Ddr1’s previously reported role in the negative regulation of CD8+ T cell migration/infiltration in carcinomas." (PMID 38652549, 2024). "Although mounting evidence supports a vital role for DDR1 in the tumorigenesis of some cancers, no pan-cancer analysis of DDR1 has been reported." (PMID 37031216, 2023). "Therefore, we investigated the pan-cancer relationship between TME and DDR1 expression, using the ESTIMATE algorithm to calculate the stromal and immune cell scores in 33 types of cancer." (PMID 37031216, 2023). "We analyzed the correlation between DDR1 expression and IC50 of over 750 anti-cancer drugs." (PMID 37031216, 2023). "It was previously demonstrated that Ddr1 could modulate the activity of the AKT/ERK pathway and plays an important role in the migration and adhesion of cancer cells." (PMID 37373466, 2023). "In addition, we assessed the relationship between DDR1 expression and PFI, a measure of how well cancer responds to palliative care." (PMID 37031216, 2023). "The results revealed that DDR1 was negatively correlated with the infiltration levels of M0 macrophages and activated CD4 T memory cells, while positively correlated with those of activated dendritic cells in TCGA pan-cancer datasets." (PMID 37031216, 2023). "DDR1 activates JNK in pancreatic cancer cells, aromatase transcription through biomechanical signals in adipose stromal cells and PI-3 kinase/Akt signals in normal, cancer cells and embryonic stem cells." (PMID 35267698, 2022).
cancer (continued). "DDR1 activation induces Src, Notch and IKK signaling pathway, DDR2 promotes oncogenic signaling via mTORC2 and AKT pathway, and recent findings have demonstrated that DDR-collagen signaling plays an important role in cancer progression and metastasis." (PMID 35008401, 2022). "When collagen interacts with cancer cell DDR1/2, a non-canonical NFκB2 (p52/RelB) resistance pathway is activated." (PMID 35267698, 2022). "Inhibiting DDR1 or DDR2 with nilotinib, dasatinib, or other non‐approved inhibitors was shown to decrease tumorigenicity, invasion, or metastasis of several carcinomas." (PMID 34957688, 2022). "NET formation and citrullinated histone H3 was induced by CCM from DDR1-expressing cancer cells exposed to collagen I but not from CCM harvested from DDR1-knockdown cancer cells after collagen I stimulation." (PMID 34237033, 2021). "DDR1 also activated proline-rich tyrosine kinase 2 (Pyk2) that ultimately induced N cadherin expression and regulated epithelial to mesenchymal transition (EMT) of cancer cells." (PMID 34966739, 2021). "Cancer cell DDR1-induced CXCL5 mediates NET formation and NET-induced cancer cell invasion." (PMID 34237033, 2021). "While there is consensus on the pro-malignant effects of DDR2 in cancer, this is not the case for DDR1." (PMID 33014862, 2020). "In contrast, aged collagen does not induce DDR1 and hence aging and proliferation occurs which can under certain circumstance lead to cancer." (PMID 32492656, 2020). "Although all these mechanisms may contribute to DDR1 aberrant expression in CRC, a miRNA-dependent epigenetic mechanism was recently documented in this cancer." (PMID 32117772, 2020). "This approach can be extended to inhibit other TM protein dimerization such as neuraminidase-1 (Neu-1, the catalytic subunit of elastin receptor complex), DDR1 (Discoidin Domain Receptor 1, a RTK activated by type I collagen) and GPCRs which are involved in cancer processes." (PMID 32351895, 2020). "As DDR1 and ADAM10 consist of a complex in cancer cells, we determined whether unmetabolized dapagliflozin directly increases ADAM10 activity for DDR1." (PMID 31979355, 2020). "Consistently, both DDR1 and DDR2 are expressed in cancers of epithelial and mesenchymal origin." (PMID 32047176, 2020). "Concerning the non-invasive epithelial-like carcinoma cells, a previous study reported a down-regulation of cell proliferation using 3D matrix, but the role of DDR1 in such a process was not explored." (PMID 32582700, 2020). "Since the fibrillar organization of type I collagen is crucial for DDR1 activation, the MT1-MMP-mediated degradation of type I collagen has been hypothesized to protect cancer cells from type I collagen-induced apoptosis." (PMID 31130862, 2019). "Therefore, anti‐DDR1 ADC probably has a certain safety and therapeutic window for targeted cancer therapies." (PMID 31116512, 2019). "Interestingly, DDR1 upregulation and AKT activation were inhibited in BC cells transfected with pre-miR-199a-5p, and as a consequence, cancer cell migration and proliferation were impaired." (PMID 30111747, 2018). "The 7rh benzamide was synthesized using a palladium-catalyzed Sonogahira coupling, and showed a significant suppressive effect on the proliferation of DDR1-expressing cancer cells, but not DDR2-, Bcr-Abl-, or c-Kit-expressing cells." (PMID 28143619, 2017). "DDR1, a non-integrin collagen tyrosine kinase receptor, is overexpressed in several malignancies and plays a role in cancer progression and metastasis." (PMID 28591735, 2017). "These new insights suggest that DDR1 and DDR2 are new potential targets in cancer therapy." (PMID 27014069, 2016).
cancer (continued). "Moreover, clinical studies on DDR1 and DDR2 expression and the outcome of several cancer pathologies found a correlation between the expression of these receptors, metastasis, and a reduced survival." (PMID 27014069, 2016). "In view of our previous results indicating that DDR1 and IGF-IR form a complex that enhances IGF-I effects in cancer cells, our present findings suggest that the IGF-IR/AKT/miR-199a-5p/DDR1 pathway is an important feed-forward mechanism for enhancing IGF-IR effects." (PMID 26655502, 2016). "In light of our results, it can be hypothesized that concomitantly high levels of DDR1 and IGF-IR may play an important role in cancer progression." (PMID 25840417, 2015). "Hence, DDR1 is a newly characterized adhesion receptor that regulates IGF-1R expression and signaling in cancer cells." (PMID 26191041, 2015). "Interestingly, the ether bridge of DDR1-IN-1 is also found in the MET (hepatocyte growth factor receptor) inhibitor LY2801653, which has entered clinical trials for advanced cancer and inhibits DDR1 with IC50 and EC50 values of less than 1 nM." (PMID 24768818, 2014). "CD44 has been shown to anchor the proteolytically-active form of MMP-9 to the cell surface while the constitutive expression of either the transcription factor ID-1 or the receptor DDR1 has been reported to increase the activity of MMP-9 and the invasiveness of human cancer cells." (PMID 21283680, 2011). "Although it is generally believed that DDR1 is more likely to act as a suppressor of oncogenic events/signaling in non-malignant cells, and as a cancer promoter in malignant cells, such a role could be reversed." (PMID 40456688, 2025). "We found that matrix deposited by cancer cells under LA stimulation, but not matrix deposited by CAFs, is supportive in inducing DDR1 activation by phosphorylation in LA-reprogrammed PCa cells, indicating that only cancer cell secreted matrix is critical in activating DDR1." (PMID 38907027, 2024). "However, DDR1 has not thoroughly studied in cancer, and its role in tumorigenesis or pan-cancer is still unclear." (PMID 37031216, 2023). "However, other studies suggest that the kinase activity is not necessary for the function of DDR1 in the cancer development." (PMID 35140331, 2022). "However, NCCM harvested from MDA-PATC 148KD#32/collagen I/neutrophil cultures failed to increase cancer cell invasion again, regardless of the DDR1 status." (PMID 34237033, 2021). "However, to our knowledge, no specific studies have addressed DDR1 role in cancer cells metabolic reprogramming." (PMID 34206590, 2021). "Here, we investigated whether DDR1 signaling has cancer cell nonautonomous effects that promote PDAC progression and metastasis." (PMID 34237033, 2021). "Indeed, by inducing the endocytosis of DDR1, LRP-1 counteracts the negative effect of DDR1 on cancer cell proliferation." (PMID 32582700, 2020). "DDR1 belongs to the family of nonintegrin collagen receptor tyrosine kinases whose deregulation is described in various diseases such as arthritis, fibrosis and the progression of various types of cancer." (PMID 32668815, 2020). "DDR1 silenced cells showed reduced adhesion to collagen type I, MMP-dependent invasion, and chemotactic and proliferative responses to collagen type I. Our work indicates an essential role for DDR1 signaling in key prometastatic features of collagen type I in human carcinoma cells." (PMID 32090682, 2020). "Additionally, immunohistochemical analysis of DDR1 in the representative tissue array of OSCC patients showed stronger positive staining in cancer tissues compared with non-cancerous tissues." (PMID 31253192, 2019). "However, the precise intracellular mechanism of DDR1-induced cancer cell aggressiveness is not clearly understood and requires further investigation." (PMID 28143619, 2017). "Moreover, DDR1 activation was shown to induce the PI3 kinase/Akt and NFκB pathways in cancer cells." (PMID 28536691, 2017).
cancer (continued). "Finally, the authors review pharmacological approaches to inhibit DDR1 and DDR2, which might represent valuable targets for anti-cancer therapies." (PMID 27148054, 2016). "Therefore, we screened TF, proto-oncogenes, tumor suppressor genes, and other TAG from the genes adjacent to aberrant DNA methylation sites, of which multiple known cancer related genes, including MYC, DDR1, MEF2C, NDRG2, SIX1, TNFRSF10B and TSGA10, had HyperM phenomena." (PMID 26046465, 2015). "Although DDR1 signaling and physiological functions are still not well understood, these studies underscore the notion that these collagen receptors can also be important mediators of cancer cell invasion, survival, and chemoresistance." (PMID 22567280, 2012). "Taken together, our work shows that targeting DDR1, BCR-ABL, or DDR1/BCR-ABL with EGFR-ERBB2 could offer a potential therapeutic strategy against WNT-activated (stem-like) and KRAS-mutant COAD, with translatable applications in stem-like refractory cancers such as GBMs." (PMID 35664781, 2022). "Collectively, our findings suggest that combinatorial targeting of DDR1/BCR-ABL with EGFR-ERBB2 signaling may offer a therapeutic strategy against stem-like KRAS-driven chemoradioresistant tumors of COAD and GBM, widening the window for its applications in mainstream cancer therapeutics." (PMID 35664781, 2022). "Interestingly, the tetraspanin TM4SF1 was found to be required for collagen-induced DDR1 clustering in cancer cells, but this clustering process did not result in DDR1 autophosphorylation, and instead led to non-canonical DDR1 signalling, independent of its kinase activity." (PMID 31745115, 2019). "It is well known that cancer and IGF-IR overexpressing cells show some basal IGF-IR tyrosine kinase activity, which may explain the effect of DDR1 in regulating to some extent responses in the absence of IGF-I stimulation." (PMID 25840417, 2015).